STAT3 (signal transducer and activator of transcription 3)
Diseases named in the same sentence as STAT3 in open-access papers (continued):
Sharing a sentence is not in itself a finding about the gene and the disease.
Sepsis (continued). "Bone marrow mesenchymal stem cells (BMSCS) -derived exosomes can deliver miR-125b-5p and reduce macrophage pyroptosis by regulating STAT3 expression, subsequently improving sepsis-induced acute lung injury." (PMID 40028334, 2025). "MAPK3, PTEN, and STAT3 were significantly upregulated in pediatric sepsis, consistent with the results of GSE145227." (PMID 40070882, 2025). "Interleukin-6 mediated sepsis-induced muscle atrophy through the gp130/JAK2/STAT3 pathway in a mouse model of sepsis, indicating the possibility of ICU-acquired weakness." (PMID 40708825, 2025). "Mechanistically, IL-6 and ROS synergistically sustained the phosphorylation of STAT3 during early sepsis, thereby initiating the activation of the Shh pathway, by which the binding of Gli1 is potentiated to the Dio3 promoter." (PMID 39877839, 2025). "The downregulation of STAT3 levels in cardiac myocytes can protect the heart by reducing inflammation and cell death in sepsis." (PMID 39823512, 2025). "We observed that targeted deletion of Stat3 significantly delayed the progression of renal injury induced by severe sepsis and 40-min bilateral renal ischaemia-reperfusion." (PMID 40344718, 2025). "Signal transducer and activator of transcription 3 (STAT3), as a converging point of multiple inflammatory responses pathways, is a crucial modulator of sepsis." (PMID 41042728, 2025). "Higher expression of Stat3 was observed in HK2 cells post-sepsis through Rela, potentially inducing ferroptosis and a worse prognosis." (PMID 40181843, 2025). "This indicates that the JAK2/STAT3 signaling pathway is involved in the pathogenesis of sepsis and the regulation of inflammation." (PMID 40338919, 2025). "STAT3 protein expression in the lung tissue was significantly elevated in the sepsis group relative to the healthy group." (PMID 39955435, 2025). "Upon examination of our results, the expression and phosphorylation of the JAK2/STAT3 signaling pathway were significantly elevated in groups with a heavy inflammatory load, such as the sepsis and TCZ16 groups." (PMID 39955435, 2025). "In patients with sepsis, the IL‐6/JAK/STAT3 pathway is highly up‐regulated and associated with muscle atrophy." (PMID 39435630, 2025). "In a cecal ligation and puncture rat sepsis model, treatment with a PPARβ/δ agonist inhibited signal transducer and activator of transcription 3 (STAT3) activation in AMs, reduced the inflammatory response, and prolonged rat survival." (PMID 40717128, 2025). "Analysis of kidney tissue revealed that the JAK2/STAT3 signaling pathway exhibited high expression in the sepsis and TCZ16 groups." (PMID 39955435, 2025). "AKT1 and STAT3 have been demonstrated as key genes in pyroptosis in sepsis, with high expression levels observed in lung tissue and lymphocytes." (PMID 39823512, 2025). "As such, in the present study, we investigated the role of STAT-3 signaling in IL-27-mediated suppression of bacterial clearance and lysosomal activity in neonatal macrophages during in vitro infection and sepsis." (PMID 40130859, 2025). "This confirmed higher Rela expression in human renal tubular epithelial cells post-sepsis via Stat3, inducing ferroptosis and a poorer diagnosis." (PMID 40181843, 2025). "STAT3, a principal transcription factor downstream of the IL-6 signaling pathway, plays a vital role in the early stages of sepsis." (PMID 39877839, 2025). "Experiments were conducted to test and confirm the high expression of Stat3 via Rela in AKI cells post-sepsis, leading to a worse prognosis." (PMID 40181843, 2025). "In conclusion, our study successfully identified MAPK3, MAPK8, PPARG, PTEN, and STAT3 as potential ferroptosis-related genes involved in the progression of sepsis." (PMID 40070882, 2025). "Inhibition of STAT-3 is particularly important, as it plays a central role in cytokine signaling during sepsis." (PMID 40699739, 2025).
Sepsis (continued). "miR-206 plays a role in modulating inflammation by regulating neutrophil recruitment in infections and alleviating inflammatory injury via the JAK2/STAT3 pathway, relevant in sepsis and other inflammatory conditions." (PMID 40621499, 2025). "STAT3 protein expression demonstrated a significant increase in the sepsis group relative to the healthy group, with a significant difference also observed between the TCZ1, TCZ8, and TCZ10 groups and the healthy group." (PMID 39955435, 2025). "Combined with sufentanil’s target protein in acute lung injury induced by sepsis, comprehensive analysis shows that the JAK2/STAT3 signaling pathway is strongly correlated with the application of sufentanil in acute lung injury induced by sepsis." (PMID 39885929, 2024). "Ulinastatin, pterostilbene, Taxifolin and Maresin1 all showed the effect of inhibiting JAK2/STAT3 signaling pathway to reduce inflammation in sepsis and protect lung injury." (PMID 39885929, 2024). "It has also been reported that ulinastatin protected rats from sepsis-induced ALI by suppressing the JAK/STAT3 signaling pathway." (PMID 37864659, 2024). "Further correlation analysis revealed a close association between MASP-1 expression, the proportion of CD8 T cells, and IL6/JAK/STAT3 signaling scores in trauma and sepsis." (PMID 38384415, 2024). "Previous studies demonstrated that the inhibition of STAT3 tyrosine phosphorylation by Stattic prevented systemic inflammation and improved survival in experimental sepsis." (PMID 38385073, 2024). "This strongly suggests that HNF4α is required to support sufficient STAT3 activity in the liver during sepsis." (PMID 39261648, 2024). "Collectively, these results provide new evidence for therapeutic approaches targeting STAT3 to improve immune status in late sepsis." (PMID 38385073, 2024). "STAT3, as a well-known transcription factor, has been previously studied for its relevance to sepsis." (PMID 38439898, 2024). "It was also reported that cuproptosis-related genes (POR, SLC7A5, and STAT3) or N6-methyladenosine (m6A) methylation were strongly involved in the pathological process of sepsis-induced cardiomyopathy." (PMID 39427197, 2024). "Meanwhile, our findings elucidate the underlying mechanisms of XBJ on sepsis-induced cardiomyocyte apoptosis and inflammation based on NF-κB and JAK2/STAT3 pathways." (PMID 37650558, 2023). "Previous studies have shown that the activated JAK2/STAT3 signaling pathway can trigger the release of pro-inflammatory and pro-apoptotic proteins during sepsis." (PMID 37650558, 2023). "Accumulating evidence indicates STAT3 to be a converging point of multiple inflammatory response pathways in sepsis pathophysiology." (PMID 37035738, 2023). "Meanwhile, atenolol also attenuated STAT3 signaling which is known to exacerbate LPS-induced sepsis." (PMID 37144032, 2023). "The inactivation of JAK2/STAT3 signaling pathway is a therapeutic target for sepsis through regulating inflammation." (PMID 37650558, 2023). "IL-6/STAT3 signaling pathway plays a critical role in sepsis, modulating the inflammatory response and coagulation." (PMID 38094883, 2023). "Specifically, LPS-induced sepsis activates acute inflammation via Toll-like receptor (TLR) pathways, while CLP-induced sepsis activates inflammation via STAT3 and cytokine expression." (PMID 37510271, 2023). "It is shown that the activation of TLR4/NF-κB and JAK2/STAT3 pathways induced apoptosis and inflammation during sepsis." (PMID 37650558, 2023). "We demonstrated that eCIRP released during a late stage of sepsis promoted endotoxin tolerance in macrophages by recognizing interleukin-6 receptor (IL-6R) and activating the STAT3 pathway." (PMID 36471113, 2023). "Our results showed that inhibition of PRMT1 downregulates the expression of COX‐2, IL‐6, sIL‐6, and p‐STAT3 in the kidney, which was induced by sepsis, revealing the regulation role of PRMT1 in inflammation and the IL‐6 trans‐signaling pathway." (PMID 37525933, 2023).
Sepsis (continued). "The expression of p‐STAT3 in the sepsis‐induced injured kidney was significantly higher than that in the sham‐operated kidney." (PMID 37525933, 2023). "The JAK2/STAT3 signaling pathway mediates IL-6 during sepsis and delivers it to particular effector cells, which are ultimately destroyed." (PMID 37650558, 2023). "Here, we identified a novel eCIRP-mediated STAT3-βPIX-Rac1 signaling pathway involved in architectural changes in macrophages that led to impaired bacterial clearance in sepsis." (PMID 36471113, 2023). "Piceatannol restored the impaired cardiac function by inhibiting the JAK2/STAT3 (Janus kinase 2/signal transducer and activator of transcription 3) pathway in cecal ligation and puncture‐induced septicemia animals and LPS‐stimulated H9c2 cardiomyocytes." (PMID 36655110, 2023). "STAT-3 is a transcription factor that regulates multiple inflammatory cascades in many infectious and autoimmunity conditions, such as sepsis." (PMID 36662218, 2023). "Second, the precise mechanisms involved in S100A8/A9 up-regulation in the lungs during sepsis and its crosstalk with the STAT3 and P38/ERK signalling pathways warrant further investigation." (PMID 37978525, 2023). "The present study is the first to establish that STAT3 signalling is regulated by S100A8/A9 in the lungs of CLP-operated mice, suggestive of a new molecular mechanism underlying sepsis." (PMID 37978525, 2023). "MiR-29a also has systemic implications in relation to sepsis by targeting STAT3, a key regulator of the inflammatory response in sepsis." (PMID 37936707, 2023). "This suggests that there is a crosstalk between the STAT3 and p38/ERK signalling pathways in sepsis, and this interaction is associated with acute lung injury and vascular permeability." (PMID 37978525, 2023). "Among these candidates, STAT3 has been reported to be involved in the pathogenesis of sepsis and S-AKI." (PMID 37095432, 2023). "Recent studies provide some evidence of therapeutic potential for targeting STAT3 in the cecal and ligature-puncture-induced sepsis model." (PMID 35742875, 2022). "Curcumin alleviated LPS-mediated sepsis by suppressing the activities of mitochondrial STAT3 and NF-κB." (PMID 34976224, 2022). "Single-cell RNA sequencing, a microarray analysis, metabolic assays, mass spectrometry and ChIP assays were utilized to gain insight into the mechanisms of mitochondrial STAT3 in metabolic reprogramming in LPS-induced sepsis." (PMID 34976224, 2022). "It seems that roflumilast guards against sepsis by suppressing STAT3, MAPK, and NF-kB signalling pathways." (PMID 35890197, 2022). "Our study results indicate that a subset of STAT3 accumulated in the mitochondrial fraction of phagocytes from sepsis patients." (PMID 34976224, 2022). "Our recent work has demonstrated that STAT3 is a therapeutic target for sepsis through regulating inflammation and coagulation." (PMID 35733865, 2022). "The regulatory function of STAT3 in sepsis has recently attracted great attention and the critical role of STAT3 in the sepsis pathophysiology has been reported in many studies." (PMID 35733865, 2022). "In a model of sepsis caused by cecal ligation and puncture, emodin protected the jejunum in rats with sepsis by activating JAK1/STAT3 signaling pathway and regulates apoptosis proteins (Bcl-2 and Bax) expression." (PMID 35744949, 2022). "Activated STAT3 promotes skeletal muscle atrophy in muscle diseases, such as muscular dystrophy, cancer, and sepsis." (PMID 35888755, 2022). "An unexpected result was that mitochondrial STAT3 exacerbated LPS-induced sepsis and promoted macrophage activation and the switch from glycolysis to an increased reliance on FAO for ATP production." (PMID 34976224, 2022). "Researchers identified STAT3 as a key regulatory gene and an important marker of sepsis-induced ARDS by analyzing whole-blood gene expression profiles of sepsis patients and sepsis-induced ARDS patients during the evolution of their disease." (PMID 35726235, 2022).
Sepsis (continued). "Regarding STAT3 phosphorylation, both groups showed an increase at the Tyr705 site during sepsis while only OVR females showed a significant phosphorylation at the Ser727 site." (PMID 35322092, 2022). "Compared to the healthy volunteers, STAT3 indeed localized in the mitochondria of phagocytes isolated from the sepsis patients, and the mitochondrial STAT3 levels were obviously enhanced in the phagocytes from the sepsis patients." (PMID 34976224, 2022). "Meanwhile, the elevated proportion of mregDCs as well as PD-L1 expression levels in sepsis were significantly attenuated following inhibition of p65 and STAT3 via specific inhibitor JSH-23 as well as SH-4-54, respectively." (PMID 35832091, 2022). "During AKI with sepsis, Stat-3 activation mediated the decrease in miR-150-5p, which enhanced renal injury." (PMID 36012630, 2022). "To compare the levels of mitochondrial STAT3 between the sepsis patients and healthy volunteers, we loaded the same amount of mitochondrial protein for SDS-PAGE." (PMID 34976224, 2022). "In summary, to the best of our knowledge, this is the first study to report that EA pre-treatment downregulates calpain-2 expression, thereby inhibiting the phosphorylation of STAT3 and improving cardiac function during sepsis." (PMID 36160853, 2022). "Curcumin protected these mice from LPS-mediated sepsis by influencing mitochondrial STAT3 function in macrophages." (PMID 34976224, 2022). "We detected STAT3 peptides in the mitochondrial fraction of phagocytes from sepsis patients and compared them with those from healthy volunteers." (PMID 34976224, 2022). "Sepsis increased the expression of calpain-2 mRNA and pro-inflammatory protein calpain-2 and p-STAT3 compared with those in the control group." (PMID 36160853, 2022). "Exosomes isolated from patients with sepsis lung injury were proven to cause lung bronchial epithelial cell injury through miR-1298-5p and its target SOCS6 via regulating STAT3 signaling pathway." (PMID 35898472, 2022). "Host inflammation responses in sepsis-associated ALI are mediated by pro-inflammatory signaling pathways, such as signal transducers and activators of transcription 3 (STAT3), extracellular signal-regulated kinase (ERK), p38, etc." (PMID 35799194, 2022). "Our recent work has demonstrated the role of signal transducer and activator of transcription 3 (STAT3) pathways in regulating inflammation and coagulation in sepsis." (PMID 35733865, 2022). "Previously, we have utilized a SOCS-1 KIR blocking peptide termed iKIR that enhanced STAT-1 and STAT-3 phosphorylation in macrophages to promote cytokine storm during sepsis." (PMID 33690673, 2021). "We have previously shown that iKIR enhances both STAT-1 and STAT-3 in a murine model of sepsis and that iKIR-mediated STAT-3 activation amplifies HIF1α-mediated glycolysis." (PMID 33690673, 2021). "Studies have shown that Stat3 and C/EBPβ synergistically induce miR-21 and miR-181b expression during sepsis." (PMID 34956174, 2021). "In recent years, JAK1/STAT3 signaling pathway has attracted more and more attention in the regulation of inflammatory response in sepsis." (PMID 34566964, 2021). "Stat3 and C/EBPβ increased miR-21 and miR-181b expression by binding to their promoters during sepsis." (PMID 34956235, 2021). "Our results further suggest that down-regulating CXCR5 can restore autophagy, polarize microglia toward the M2 phenotype, and inhibit p38MAPK/NF-κB/STAT3 signaling, ultimately attenuating sepsis-induced neuroinflammation and cognitive dysfunction." (PMID 34711216, 2021). "In recent years, the significance of JAK1/STAT3 signaling involved in regulating inflammation and injury of sepsis attracted more attention due to its simple and effective activation." (PMID 33506010, 2021).
Sepsis (continued). "It was found that an increased level of exogenous IL-13 was beneficial to the recovery of heart function in sepsis, and this anti-apoptotic effect of IL-13 was probably through enhancing the phosphorylation of STAT3 Ser727." (PMID 34616745, 2021). "Our study not only evaluated the therapeutic effect of ZJF on lung injury induced by sepsis but also provided a new perspective for resolving the mechanism of ZJF in regulating the JAK1/STAT3 signaling pathway." (PMID 33506010, 2021). "Further in-depth analysis of the regulatory function of the STAT3 pathway in sepsis will be the focus of future research." (PMID 32641132, 2020). "We demonstrated that pharmacological intervention with the STAT3 inhibitor stattic mimicked the beneficial effect of STAT3 decoy ODNs on major end-organ tissue injury in mice with CLP-induced sepsis." (PMID 32943679, 2020). "We showed that in vivo transfection of STAT3 decoy ODNs minimized the development of major end-organ injury in mice with CLP-induced sepsis and resulted in a prominent survival advantage in the animals after CLP." (PMID 32943679, 2020). "T cells are primed to promote IL-17 production by increasing STAT3-mediated transcriptional regulation in the lungs of mice with sepsis." (PMID 32293300, 2020). "Meanwhile, in the animal study, data presented that administration of Ade-HIF-1α resulted in an increased expression of HIF-1α and STAT3 compared with the sepsis rat model group and the Ade-control group." (PMID 32089644, 2020). "miR-223, as a pro-inflammatory factor, is involved in several signaling pathways that control inflammatory responses and infection reaction activation, such as negative regulation of STAT3 and IL-6 expression during sepsis." (PMID 33292630, 2020). "The elevation in these serum aminotransferase levels after sepsis was significantly decreased in CLP mice given STAT3 decoy ODN." (PMID 32943679, 2020). "In this study, we introduced in vivo synthetic double-stranded decoy ODN containing selective STAT3 protein dimer binding consensus sequences into mice with CLP-induced sepsis." (PMID 32943679, 2020). "We should also focus on the role of negative regulators of the STAT3 pathway in the treatment of sepsis." (PMID 32641132, 2020). "In conclusion, our present work provides evidence that STAT3 plays a critical role in the pathophysiology of sepsis." (PMID 32943679, 2020). "Our results suggest a critical role of STAT3 in the sepsis pathophysiology and the potential usefulness of STAT3 decoy ODNs for sepsis gene therapy." (PMID 32943679, 2020). "While our results showed that pY-STAT3 is a promising therapeutic target in sepsis, the role of STAT3 as an essential transcription factor makes the development of pSTAT3-targeted therapies challenging." (PMID 32641132, 2020). "For sepsis, we noticed several inflammatory and immune-related proteins, such as IRAK1, IRAK3, IKBKB, and STAT3, in the network, suggesting overlap of the inflammatory response activated in COVID-19 and sepsis." (PMID 33156843, 2020). "The HMGB1 mRNA levels were also upregulated in tissues from mice with CLP-induced sepsis, which was significantly reversed by treatment with STAT3 decoy ODNs." (PMID 32943679, 2020). "Previous studies have shown that JAK2 and STAT3 are activated in an experimental mammalian sepsis model." (PMID 32641132, 2020). "We also demonstrate that transfection of STAT3 decoy ODNs affords protection against the development of sepsis-driven major end-organ injury and leads to a prominent survival advantage in mice after CLP." (PMID 32943679, 2020). "In murine sepsis, IL-10 has been reported to suppress the expression of IL-27 by activated F4/80+CD11b+ macrophages in an STAT3-dependent pathway." (PMID 31214168, 2019). "In the cecal ligation and puncture rat sepsis model, treatment with a PPARβ/δ agonist inhibited signal transducer and activator of transcription 3 (STAT3) activation in AMs, reduced the inflammatory response, and prolonged rat survival." (PMID 30897154, 2019).